CXCR4 (C-X-C motif chemokine receptor 4)
Diseases named in the same sentence as CXCR4 in open-access papers (continued):
Sharing a sentence is not in itself a finding about the gene and the disease.
lymphoma (continued). "The upregulation of CXCR4 contributes to the increased migratory and invasive capabilities of lymphoma cells, facilitating their spread and complicating treatment." (PMID 40076664, 2025). "In conclusion, our results illustrate the complex interplay between CD19 and CXCR4 in lymphoma pathophysiology and therapeutic response." (PMID 40076664, 2025). "The B cell homeostatic receptors, CCR7 and CXCR4, contribute to the formation of a supportive niche for lymphoma cells, promoting tumor survival, proliferation, and early relapse." (PMID 40896244, 2025). "Our observation aligns with a previous study demonstrating CXCR4 upregulation upon in vitro CD30 stimulation of a CD30+ Hodgkin-Lymphoma cell line." (PMID 39420111, 2024). "In hemato-oncology, recent efforts also turned towards “cold” CXCR4 inhibitory therapies, e.g., by investigating CXCR4 antagonist IgG1 antibodies, which achieved substantial anti-lymphoma effects by disrupting SDF1 pathways." (PMID 37286923, 2023). "CXCL12 and its receptor CXCR4 are among the main factors regulating lymphoma cell trafficking from blood to lymphoid tissue." (PMID 36900374, 2023). "Both CXCR4 pepducins, including those in combination with the anticancer drug rituximab, suppressed the survival and metastasis of disseminated lymphoma xenografts." (PMID 37047169, 2023). "In this regard, CXCR4-targeted radioligand therapy (RLT) based on pretherapeutic PET/CT has already achieved outcome benefits in end-stage lymphoma patients, thereby rendering this theranostic concept favorable for the referring hemato-oncologist." (PMID 37286923, 2023). "Multiple studies have demonstrated the imaging and targeting capabilities of 68Ga-Pentixafor for CXCR4-expressing lymphomas." (PMID 36831405, 2023). "PF-06747143, a CXCR4 inhibiting IgG1 antibody, inhibits the signaling pathway and cell migration of lymphoma cells, reducing the bone marrow infiltration of Burkitt’s lymphoma in vivo." (PMID 35303910, 2022). "Pepducins designed to target CXCR4 exhibited in vitro and in vivo efficacy in several disease models,including lymphoma." (PMID 38239337, 2022). "Upon subcutaneous administration in a mouse model of human CXCR4+ lymphoma, the protein–drug depots release nanoconjugates for at least 10 days, which accumulate in the tumor with a potent antitumoral effect." (PMID 35057088, 2022). "Lymphomas are lymphoproliferative diseases with a high CXCR4 expression and are consequently suitable for evaluation with a CXCR4-targeted imaging technique." (PMID 35954476, 2022). "We demonstrate here that CXCR4-mediated migration of lymphoma cells towards CXCL12 requires the expression of functional ACKR3 at the cell surface." (PMID 36713377, 2022). "Several antibodies have been developed for T cell NHL (e.g., alemtuzumab (anti-CD52), brentuximab (anti-CD30), and mogalizumab (anti-CXCR4)), all of which mediate at least part of their anti-lymphoma efficacy through ADCC." (PMID 35258793, 2022). "In this study, we were able to show that CD20-positive lymphoma cells in a PCNSL PDX homing mouse model with a PVRL phenotype co-express the chemokine receptors CXCR4, CXCR5 as well as CD44 in comparison to a SCNSL PDX mouse model." (PMID 36233057, 2022). "Somatostatin receptors (SSTR) and chemokine receptor CXCR4 are expressed in lymphomas, while the abundance is known to be heterogeneous in different subtypes of lymphomas." (PMID 34307181, 2021). "This mutation is characteristic for WHIM-syndrome (warts, hypogammaglobulinemia, infections, myelokathexis) patients and allows the investigation of CXCR4 hyperactivation on B-cell lymphoproliferation and lymphoma development." (PMID 34363012, 2021). "SSTR 2, 3 and 5 and CXCR4 expression was analyzed immunohistochemically (IHC) in lymphoma samples obtained from local archival Biobank tissue repository." (PMID 34307181, 2021). "This further indicates a B-cell-specific influence of CXCR4 signaling toward a more aggressive lymphoma phenotype." (PMID 34363012, 2021).
lymphoma (continued). "In cell-culture based studies CXCR-4 dependent interaction of lymphoma cells with stromal cells has been shown to protect lymphoma cells from anti-CD20 monoclonal antibody induced apoptosis." (PMID 34956859, 2021). "Using the Eμ-Myc lymphoma model, we showed that CXCR4 transcript and surface expression is enhanced by oncogenic MYC." (PMID 34363012, 2021). "In this article we provide evidence that a naturally occurring peptide, called EPIX4 and its optimized derivatives bind to CXCR4 on Waldenström’s macroglobulinemia cells and are able to impair growth of these lymphoma cells in mice." (PMID 33669329, 2021). "Specifically, chemokine receptor CXCR4 along with its ligand stromal-derived factor-1 (CXCL12) is involved in signaling pathways of several hematologic malignancies including lymphomas." (PMID 34307181, 2021). "We conclude that CXCR4 activation is an integrative hallmark of aggressive MYC-driven lymphoma, and show that MYC translocation and MYC expression correlate with increased CXCR4 expression." (PMID 34363012, 2021). "To investigate if the effects of CXCR4 hyperactivation on B-cell leukemia and lymphoma development and dissemination are B cell intrinsic, we isolated splenocytes of pre-malignant animals and assessed their migratory capacity in response to CXCL12 ex vivo." (PMID 34363012, 2021). "On immunohistochemical staining, lymphoma cells were positive for CXCR4 and adenocarcinoma cells were positive for CXCL12/SDF-1." (PMID 34187383, 2021). "In this study, we employed the Eμ-TCL1 and Eμ-Myc mouse models to interrogate the role of hyperactivated CXCR4 signaling in B-cell lymphoproliferation and B-cell leukemia/lymphoma pathogenesis." (PMID 34363012, 2021). "Eμ-Myc lymphoma cells displayed significantly increased CXCR4 surface expression compared to normal B cells and Eμ-TCL1 lymphoma cells, indicating a potential link between MYC and CXCR4 expression." (PMID 34363012, 2021). "In conclusion, SSTR and CXCR4 expression is heterogenous and varies considerably within different lymphoma subtypes." (PMID 34307181, 2021). "In summary, we here identify CXCR4 hyperactivation as a co-driver of an aggressive lymphoma phenotype." (PMID 34363012, 2021). "Next, we sought to determine if enhanced CXCR4 activity would also result in a more accelerated lymphoma biology in a model of aggressive lymphoma." (PMID 34363012, 2021). "CXCR4 regulates tissue trophism of lymphoma cells and protects them from chemotherapy-induced apoptosis by promoting leukemic blasts homing into BM niches." (PMID 32260318, 2020). "This animal model, which was generated by the intravenous injection of Toledo-Luci cells and described in detail in our previous work, shows CXCR4 overexpression in all organs infiltrated by lymphoma cells." (PMID 32373205, 2020). "For the indolent lymphomas, the patients with Waldenström’s macroglobulinemia all had the hallmark MYD88 mutation, and three of those also had a CXCR4 mutation, both very frequent mutations in this disease." (PMID 32013121, 2020). "We think these results have provided strong evidence of the mechanism of CXCR4-mediated [68Ga]pentixafor uptake in lymphoma." (PMID 32757068, 2020). "An improved T22-GFP-H6 uptake was also shown in CXCR4+ lymphoma cells affecting LNs and BM in a disseminated DLBCL mouse model." (PMID 32373205, 2020). "Previous studies have determined that [68Ga]pentixafor binded with high specificity and selectivity to human CXCR4 and CXCR4 expression was correlated with cellular uptake of [68Ga]pentixafor in lymphoma cell lines." (PMID 32757068, 2020). "CXCR4 expression is also detected in malignant lymphoma cell lines, and its inhibition by a monoclonal antibody enhances apoptosis, decreases proliferation, and inhibits migration." (PMID 30755239, 2019). "It is known that CXCR4 is upregulated under hypoxic conditions in lymphoma and several other cell lines in vitro." (PMID 31554271, 2019).
lymphoma (continued). "Since data on this axis in diffuse large B cell lymphoma (DLBCL) are inconsistent and limited, we comprehensively studied the CXCR4-CXCL12-axis in our DLBCL cohort as well as the effects of CXCR4 antagonists on lymphoma cell lines in vitro." (PMID 31554271, 2019). "Both WK1 and AMD070 showed pro-apoptotic effects, which were especially more pronounced in the CXCR4+ lymphoma cell lines treated with WK1." (PMID 31554271, 2019). "We also demonstrated that CXCL12 expression correlated to the BM infiltration rate and that CXCR4 was lower expressed in BM samples from patients exhibiting a remission of lymphoma infiltration after therapy." (PMID 31554271, 2019). "WK1 demonstrated stronger pro-apoptotic effects than AMD070 in vitro and induced expression of pro-apoptotic genes of the BCL2-family in CXCR4-positive lymphoma cell lines." (PMID 31554271, 2019). "In corresponding bone marrow biopsies, we observed a correlation of CXCL12 expression and lymphoma infiltration rate as well as a reduction of CXCR4 expression in remission of bone marrow involvement after treatment." (PMID 31554271, 2019). "Comparison of CXCR4 and CXCL12 mRNA expression levels in BM specimens with and without lymphoma infiltration at time of diagnosis showed a 1.6-fold higher CXCR4 expression in BM specimens exhibiting lymphoma infiltration (p = 0.008)." (PMID 31554271, 2019). "To validate these findings, we treated all four lymphoma cell lines with the three CXCR4 antagonists at concentrations of 1 μM, 5 μM, 10 μM, 20 μM, and 40 μM." (PMID 31554271, 2019). "For example, several genes previously identified in other types of lymphomas, such as NOTCH1, POU2F2, CXCR4, and IGF1R, were affected by mutations." (PMID 28152507, 2017). "Coinjection of 2 mg/kg AMD3100 (white bars) resulted in a reduction of tumor uptake by 88% (1.5 h p.i.), demonstrating the high CXCR4-specificity of [64Cu]NOTA-pentixather accumulation in the lymphoma xenograft." (PMID 29527563, 2017). "Lymphoma cells express the C-X-C chemokine receptor type 4 (CXCR4), which mediates cell migration to organs expressing its ligand C-X-C motif chemokine 12 (CXCL12)." (PMID 29245936, 2017). "CXCR4 expression was present in approximately 50% of lymphoma cells and showed a perinuclear expression pattern." (PMID 28577295, 2017). "The PET MRI with the novel CXCR4-directed tracer [68Ga]Pentixafor showed specific uptake (SUVmax of 5.9, TTB 2.6) within the CXCR4-positive lymphoma manifestation." (PMID 28577295, 2017). "This was selected for CXCR4high lymphoma cells due to the dynamics of CXCL12/CXCR4 equilibrium and led to decreased T cell infiltration and deficient immune responses due to reduced chemoattraction, cooperating with the CXCR4-associated pro-survival signals." (PMID 25704881, 2015). "The prognostic significance of CXCR4 expression in lymphoma, which has different CXCL12 gradients at the primary sites compared to other types of cancers, has not been well studied." (PMID 25704881, 2015). "They noticed significant lower expression of CXCR4 in Waldenström Macroglobulinemia (WM) in comparison to other lymphomas." (PMID 24859274, 2014). "The cell-surface CXCR4 receptors on lymphoma and HeLa cells are rapidly internalized, and approximately 100% of the cell-surface CXCR4 pools are exchanged every 5 h (in lymphoma cell lines) and 40 min (in HeLa cells)." (PMID 24516533, 2014). "Response evaluation and re-staging of lymphoma patients after therapy in relation to bone marrow CXCR4 expression changes." (PMID 24859274, 2014). "Decreased CXCR4 resulted in disrupt lymphoma and host bone marrow-derived stromal cells CXCR4/CXCL12 axis, what resulted in stroma-induced protection from immunotherapy infringement." (PMID 24859274, 2014). "Basing on our results it is difficult to decide, if highly expressed CXCR4 reflects lymphoma tumor burden or mirrors the role of host immune cells." (PMID 24859274, 2014).
lymphoma (continued). "In 46 out of 51 analyzed node homogenates (lymphoma and reactive lymph nodes) high CXCR4 expression was observed." (PMID 24859274, 2014). "They observed lower CXCR4 expression in patients with diseases where circulating lymphoma B-cells are found less frequently (diffuse large B-cell lymphoma or WM)." (PMID 24859274, 2014). "Another group found that CXCR4 expression was positive in all the analyzed cases of lymphomas, however, considerably higher in e MCL, B-CLL and HCL." (PMID 24859274, 2014). "The purpose of this study was to determine CXCR4 gene expression in lymphoma infiltrated lymph nodes in comparison to reactive lymph nodes." (PMID 24859274, 2014). "The missing lymphoma sink effect may also be related to dosing studies using novel CXCR4 inhibitors as “cold” drugs." (PMID 40427609, 2025). "CXCR4 overactivation is a co-driver of the aggressive lymphoma phenotype." (PMID 40427609, 2025). "However, the enhanced migration capabilities of lymphoma cells toward CXCL12 indicate that CD19’s signaling interaction with CXCR4 is a crucial mechanism in lymphoma cell chemotaxis." (PMID 40076664, 2025). "For therapeutic applications, anti-lymphoma efficacy exerted by CXCR4 RLT may be useful in advanced and treatment-refractory TCL." (PMID 38190998, 2024). "In addition to nodal lymphoma manifestations above and below the diaphragm, there is a CXCR4-positive lymphoma manifestation in the intestine." (PMID 39090381, 2024). "As such, CXCR4-mediated RLT may serve as an effective conditioning therapy for HSCT with concurrent anti-lymphoma activity in treatment-refractory TCL in advanced disease setting." (PMID 38190998, 2024). "Thus, this lymphoma subtype has been extensively evaluated using the theranostics CXCR4 PET probe [68 Ga]Ga-PentixaFor to report on the current status of chemokine receptor expression." (PMID 39090381, 2024). "Moreover, chemokine receptors CXCR7 and CXCR4 from TEC facilitate lymphoma and BCC transendothelial migration under the control of TEC." (PMID 38515582, 2024). "In lymphoma, CXCR4 recruits Tregs to the tumor mass, possibly through CCL17 and CCL22." (PMID 39000453, 2024). "Future efforts such a revised version of the harmonization project in lymphoma may also include reporting criteria for CXCR4-directed PET/CTs." (PMID 39090381, 2024). "Second, aggressive lymphomas with involvement of the central nervous system may benefit from CXCR4-directed PET/CT, as the use of 18F-FDG is hampered by the physiologic biodistribution of 18F-FDG in the central nervous system." (PMID 37290799, 2023). "We observed no relevant associations between normal organ uptake and CXCR4-positive lymphoma burden in patients with MZL studied with [68Ga]Ga-PentixaFor PET/CT." (PMID 37286923, 2023). "As such, future studies may also evaluate a potential lymphoma-sink effect in other subtypes, in particular in those which have already benefitted from CXCR4-RLT, including T-cell lymphoma." (PMID 37286923, 2023). "Beyond improved detection rates of putative sites of disease, C-X-C motif chemokine receptor 4–directed PET/CT also selects candidates for radioligand therapy using β-emitting radioisotopes targeting the identical chemokine receptor on the lymphoma cell surface." (PMID 37290799, 2023). "This CXCR4-directed theranostic concept has been used as a conditioning regimen prior to hematopoietic stem cell transplantation and to achieve sufficient anti-lymphoma/-tumor activity in particular for malignant tissues that are highly sensitive to radiation, such as the hematological system." (PMID 35674738, 2022). "However, the use of these regimens is limited to CXCR4 + lymphomas like CXCR4 + disseminated refractory or relapsed DLBCL patients." (PMID 35303910, 2022). "In summary, CXCR4 was expressed by CD20-positive lymphoma cells in our PCNSL/PVRL model." (PMID 36233057, 2022). "In all, CXCR4 antagonists can reduce tumor burden and the dissemination of lymphoma to organs." (PMID 35303910, 2022).
lymphoma (continued). "Besides, the consequence of active CXCR4 signaling in lymphoma also involves oncogenesis and confers resistance to PI3Kδ inhibitor, which is disrupted by a missense mutation in DHL-BCL6." (PMID 35303910, 2022). "In our study, the 15% proportion of CD20/CXCR4-positive cells in all CD20-positive lymphoma cells may have negatively impacted the expression of CD44 on lymphoma cells." (PMID 36233057, 2022). "In the light of recent findings linking active Akt signaling, a downstream target of CXCR4, to Richter’s transformation, it seems possible that Akt phosphorylation by hyperactivated CXCR4 is a contributing factor for the aggressive lymphoma phenotype in our CXCR4 hyperactivation models." (PMID 34363012, 2021). "However, both SSTR2 and CXCR4 are commonly expressed in DLBCL, FL and HL rendering these lymphomas - when receptor positive - potential candidates for treatments targeting SSTR2/CXCR4." (PMID 34307181, 2021). "SSTR2, 3, 5 and CXCR4 IHC results in studied lymphoma subtypes." (PMID 34307181, 2021). "Compared to SSTR, the role of CXCR4 has been studied more recently in lymphomas, especially in DLBCL, where CXCR4 upregulation has been shown to be associated with tumor cell dissemination, disease progression, and poor survival and also with impaired response to rituximab treatment." (PMID 34307181, 2021). "We undertook current study to characterize SSTR and CXCR4 expression in 103 patients with lymphoma." (PMID 34307181, 2021). "Finally, survival of patients with lymphomas co-expressing SSTRs and CXCR4 should be studied to establish the prognostic role of these biomarkers in more detail." (PMID 34307181, 2021). "Despite a plethora of evidence linking CXCR4 to the pathogenesis of CLL and DLBCL, it is unknown if and how enhancing CXCR4 pathway activity can alter the course of B-cell lymphoproliferation, and B-cell leukemia/ lymphoma development and progression." (PMID 34363012, 2021). "We have developed a therapeutic nanostructured protein T22-PE24-H6 that incorporates exotoxin A from Pseudomonas aeruginosa, which selectively targets lymphoma cells because of its specific interaction with a highly overexpressed CXCR4 receptor (CXCR4+) in DLBCL." (PMID 32373205, 2020). "In addition, repeated T22-PE24-H6 intravenous administration in a CXCR4+ DLBCL-disseminated mouse model showed a significant reduction of lymphoma burden in organs clinically affected by DLBCL cells (lymph nodes and bone marrow)." (PMID 32373205, 2020). "Thus, a significant reduction in lymphoma dissemination in T22-PE24-H6-treated mice compared to mice treated with buffer is observed in the organs infiltrated by CXCR4+ DLBCL cells (LNs and BM)." (PMID 32373205, 2020). "We then tested whether fluorescent labeling could significantly disturb the CXCR4-mediated endosomal cell internalization of nanoparticles in CXCR4+ human Toledo lymphoma cells." (PMID 33105866, 2020). "Inhibition of the CXCL12/CXCR4 axis significantly inhibited lymphoma proliferation and survival, suggesting that the CXCR4/CXCL12 axis may participate in EBV-associated lymphomagenesis." (PMID 33052232, 2020). "Furthermore, we observed a 4.7-fold higher CXCR4 expression in lymphomas with an advanced stage (stage 2–4) compared to DLBCL patients with clinical stage 1 (p = 0.028)." (PMID 31554271, 2019). "The data on BM samples with or without involvement of DLBCL of our cohort showed a downregulation of CXCR4 in the BM of patients under remission after therapy as well as the correlation of the CXCL12 expression with lymphoma cell infiltration underpins this assumption." (PMID 31554271, 2019). "Besides receptor antagonists that directly inhibit leukemic cell proliferation, preclinical and clinical studies demonstrate that CXCR4 inhibition mobilizes leukemic-lymphoma cells from their niches, improving conventional chemotherapy efficacy." (PMID 28947904, 2017).